BRAF (B-Raf proto-oncogene, serine/threonine kinase)
Diseases named in the same sentence as BRAF in open-access papers (continued):
Sharing a sentence is not in itself a finding about the gene and the disease.
melanoma (continued). "In a recent paper on melanoma, tumor heterogeneity has been simulated in vivo by an admixture of 0.05% of A375 BRAF inhibitor-resistant melanoma cells to 99.95% of A375 BRAF inhibitor-sensitive melanoma cells." (PMID 33535416, 2021). "For melanoma, previous work has shown that intermittent dosing of a BRAF inhibitor, vemurafenib, given to patient-derived mouse model systems, controlled tumor volumes significantly better than continuous therapy." (PMID 33669315, 2021). "Copy number of BRAF gene was significantly correlating with increasing BRAF MAF values in visceral melanoma metastases compared to the matching primary tumors, especially in case of lung metastases." (PMID 34885093, 2021). "To this end, we injected the BRAF-mutant melanoma cell line A375 subcutaneously into the flanks of the athymic nude mice and treated them with either carmofur alone, vemurafenib alone, or a combination of carmofur and vemurafenib." (PMID 33766731, 2021). "The presence of certain BRAF mutations (e.g., BRAFT1799A) in malignancies such as melanoma and lung cancer serves as a predictive biomarker for the clinical deployment of vertical inhibitors of BRAFV600E signaling." (PMID 34298710, 2021). "The actin remodelling dynamics of TESK1 confers BRAF inhibitor (PLX4032) resistance to melanoma cells through YAP/TAZ activation." (PMID 33799345, 2021). "In patients with rapidly progressive and/or (severe) symptomatic BRAF-mutant melanoma, BRAF-directed therapy is often prescribed as first-line treatment." (PMID 33765967, 2021). "Inhibition of IGF2BP1 expression further promoted the treatment efficacy of a BRAF inhibitor and reduced the tumorigenicity of vemurafenib-resistant melanoma cells." (PMID 34203267, 2021). "In patients with wild type BRAF melanoma, the RR was 61% in the group of patients who received combination therapy compared to 11% of patients who received ipilimumab + placebo (P <0.001), with complete responses." (PMID 34447613, 2021). "BRAF inhibitor treatment in melanoma promoted the reduction activity of the MAPK/ERK pathway, which is responsible for tumor proliferation and survival." (PMID 33408768, 2021). "It has been observed that the mutated oncogene BRAF can regulate MITF expression, thus ensuring protein levels compatible with the proliferation and survival of melanoma cells." (PMID 34203771, 2021). "The extracellular visfatin level decreased the response to therapy with BRAF/MEK inhibitors but increased again upon melanoma progression and development of BRAFi resistance." (PMID 34068679, 2021). "These authors compared baseline tumor features of melanoma patients who had either complete response or fast progression after treatment with BRAF and MEK inhibitors." (PMID 33407577, 2021). "Melanoma patients treated with BRAF and MEK inhibitors frequently develop an exanthema, also referred to as “skin rash” by non-dermatologists." (PMID 34109122, 2021). "It is possible that HDAC8 induces PLCB1 through deacetylating/activating c-JUN, as in the BRAF inhibitor-resistant melanoma." (PMID 34064422, 2021). "By considering both PLA1A mRNA and serum levels simultaneously, PLA1A levels were significantly increased in BRAF/NRAS+ melanoma patients (p ≤ 0.05)." (PMID 33723350, 2021). "Mice fed the prebiotics inulin or mucin also demonstrated changes in gut microbes, anti-tumour immune responses, and inhibition of BRAF mutant melanoma growth." (PMID 34960140, 2021). "The determination of BRAF V600 status is mandatory in patients with resectable or unresectable stage III or IV melanoma (Level of evidence 1, grade of recommendation A)." (PMID 34440462, 2021). "Despite the remarkable responses of BRAF mutant melanoma patients to BRAF and MEK inhibitors, primary resistance or development of acquired resistance to these targeted therapies remain a significant issue." (PMID 34440905, 2021).
melanoma (continued). "Previous studies found similar results in heterogeneous cohorts of melanoma patients, irrespectively of their BRAF status." (PMID 34552135, 2021). "Assessing TILs through deep learning showed a predictive value in BRAF V600E/K melanomas that received CPI treatment from a single center." (PMID 33469107, 2021). "We exposed BRAF mutant melanoma cell lines A375, WM115, and WM983B to increasing concentrations of the BRAF inhibitor dabrafenib and the MEK inhibitor trametinib." (PMID 34831014, 2021). "BRAF V600 mutations are usually associated with a more aggressive disease and a shorter survival in stage IIIB, IIIC radically resected and even stage IV melanoma, potentially arguing for their prognostic role." (PMID 35008245, 2021). "A synergistic effect of EO05 followed by trametinib was also obtained in the BRAF wild type melanoma cells, ME4405 (CI = 0.6)." (PMID 34059622, 2021). "Nevertheless, melanoma cells adapt to the blocking of BRAF and MEK, becoming able to thrive even under pharmacological pressure." (PMID 33407577, 2021). "The activators and components of the MAPK pathway—Raf, RAS, BRAF, MEK, and ERK—are frequently mutated in colon, melanoma, ovarian, thyroid, colorectal, and non-small cell lung cancers." (PMID 34829731, 2021). "Vemurafenib and dabrafenib are two selective V600 mutant BRAF inhibitors that have been deployed for the treatment of V600E+ tumors, including melanoma, colorectal cancer, and non-small cell lung cancers." (PMID 33807608, 2021). "Skp2 depletion in melanoma cells resulted in a G2-M phase arrest, and suppression of both BRAF (V600E) and Skp2 inhibited cell growth and invasion in melanoma cell lines." (PMID 33841154, 2021). "BRAF-mutated melanoma can be treated with BRAFi and is more sensitive to ICI than BRAF-wild-type melanoma." (PMID 33478111, 2021). "In summary, we identified a considerable number of patients who achieved a CR upon BRAF/MEK-directed TT in this contemporary real-world cohort of patients with BRAF-V600-mutant melanoma." (PMID 34065877, 2021). "In the current study, we administered two well-studied mitochondria-targeted antioxidants, MitoQ and MitoTEMPO, to mice with BRAF-induced malignant melanoma and KRAS-induced lung cancer, and defined their impact on tumor progression and metastasis." (PMID 33499262, 2021). "The drug is approved for the treatment of unresectable or metastatic BRAF V600E melanoma as a single agent or in combination with the MEK inhibitor Trametinib." (PMID 33557011, 2021). "We will also discuss current novel therapeutic approaches that are underway to target non-BRAF mutant melanomas." (PMID 34831002, 2021). "Particularly, a hyperactivation in EGFR and MET in cells with acquired resistance to BRAF inhibitors was shown; consequently, this combination (lapatinib+foretinib) was tested for its efficiency in BRAF resistant melanoma cells." (PMID 33918490, 2021). "In this study we shed light onto the therapeutic perspective of a small linear octopus peptide as a potential drug candidate targeting BRAF (V600E) melanoma." (PMID 33672955, 2021). "The suppression of p-RPS6 has been identified as a predictive marker for improved progression-free survival (PFS) in BRAF-mutant melanoma treated with RAF or MEK inhibitors." (PMID 35008473, 2021). "The top 10 mutated genes in melanoma were TTN (72%), MUC16 (67%), DNAH5 (49%), PCLO (44%), LRP1B (38%), ANK3 (32%), DNAH7 (32%), ADGRV1 (35%), RP1 (33%), and BRAF (51%)." (PMID 33758620, 2021). "In our study, we aim to describe the efficacy of neoadjuvant BRAF-oriented targeted therapy in patients with borderline resectable melanoma in real-world clinical practice." (PMID 35008274, 2021). "While most of this work focused on BRAF melanoma cell lines, MEK inhibition in NRAS mutant melanoma cell lines was also found to activate cytoprotective autophagy through ERK reactivation." (PMID 34830283, 2021).
melanoma (continued). "By contrast, pri-miR-29b2~c levels significantly decreased in BRAF-mutant melanocytes and melanoma cells compared to wildtype melanocytes." (PMID 33808771, 2021). "In Ontario, testing for predictive biomarkers including EGFR for lung adenocarcinoma, BRAF in malignant melanoma and KRAS and BRAF in metastatic colorectal cancer supports the use of targeted therapies for these patients." (PMID 34597339, 2021). "The plasmatic levels of other ncRNAs such as lncRNAs (IGF2AS, anti-Peg11, MEG3, Zeb2NAT) were also found to be associated with prognosis and therapy response in BRAF-mutant advanced melanoma patients treated with the BRAF inhibitor vemurafenib." (PMID 34208598, 2021). "We report on a large series of 106 consecutive melanoma patients with BM receiving systemic therapy of ICI or anti-BRAF inhibitors." (PMID 34503304, 2021). "A BRAF-mutant melanoma cell line was treated with BRAFi, and analyses were made at different time points (days/D0, D1, D3, and D5)." (PMID 33535416, 2021). "Paired biopsy samples from BRAF mutant melanoma patients treated with BRAF inhibitors (BRAFi) showed increased levels of autophagy in BRAFi-resistant compared to BRAFi-responsive tumors." (PMID 34298710, 2021). "The accumulation of genetic and epigenetic changes including BRAF and NRAS mutations is thought to drive melanoma progression." (PMID 33446631, 2021). "Treatment of BRAF mutant melanoma with BRAF inhibitor reduced expression of GLUT-1, thereby suppressing tumor activity." (PMID 33420213, 2021). "We found that expression of PMCA4b in A375 BRAF mutant melanoma cells induced a profound change in cell shape, cell culture morphology, and displayed a polarized migratory character." (PMID 33802790, 2021). "In BRAF inhibitor-treated melanoma cells, MITF was differentially expressed to promote proliferation (high MITF to induce MLANA, PMEL, TYRP genes) or invasion (low MITF to induce high AXL, WNT5A, TEAD, JUN expression)." (PMID 34066022, 2021). "Further experiments in cell lines and nude mice bearing xenografts of BRAF mutant melanoma confirmed that bilirubin is able to strongly restrain the anticancer effect of vemurafenib." (PMID 34222023, 2021). "Activation of EGFR will stimulate melanoma cells to progress or metastasize and be resistant to BRAF inhibitors." (PMID 34745259, 2021). "High MITF expression sensitizes melanoma cells to BRAF and MEK inhibitors whereas the cells are more proliferative." (PMID 35127523, 2021). "For example, a network analysis revealed the underlying molecular, tumor type-specific networks accounted for different responses to the inhibitor targeting BRAF V600E in melanoma and colorectal cancer." (PMID 34097054, 2021). "The addition of cyclin-dependent kinase 4/6 inhibitors to combination BRAF-MEK inhibitors can also greatly improve the duration of response against melanoma." (PMID 34944961, 2021). "The combined use of BRAF and MEK inhibitors is one of the standards of care for patients with advanced BRAF-mutant melanomas." (PMID 33525348, 2021). "We also demonstrate that pharmacological ASAH1 inhibition blocks melanoma growth and increases the effectiveness and therapeutic duration of a BRAF kinase inhibitor." (PMID 33766731, 2021). "In BRAF (V600E) mutant melanoma cells, DHODH modulates transcriptional elongation and its inhibition completely abrogated cell growth, providing the potential therapeutic strategy through combination of DHODH and BRAF (V600E) inhibitors." (PMID 34123854, 2021). "In the present study, we assessed the role of mTORC2/RICTOR in BRAF-mutated melanoma and showed that RICTOR stimulated melanoma-initiating cells (MICs) with ‘stemness’ properties." (PMID 34680615, 2021). "Therapy for melanoma has experienced a revolution as a result of targeted therapies with BRAF and MEK inhibitors and immunotherapies with checkpoint inhibitors." (PMID 34663263, 2021).
melanoma (continued). "As a result, melanoma cells acquire improved tumorigenic capacities due to apoptosis suppression and BRAF inhibitor resistance." (PMID 34827551, 2021). "Further, profiling of BRAF mutant melanomas with acquired resistance to BRAF and MEK inhibitors found that ABL kinase activity was increased in therapy resistant cells." (PMID 34022881, 2021). "Both structureless white areas and peppering have been described more frequently in BRAF and NRAS mutated melanomas than in wild type." (PMID 34440462, 2021). "The screened population consisted of 53 patients with BRAF-mutant melanoma who were treated with initial CKI treatment." (PMID 34743688, 2021). "Taken together our results emphasize miR-129-5p, as well as SOX4, as potential therapeutic targets in BRAF-driven melanoma." (PMID 34063443, 2021). "NRAS-mutant melanomas preferentially localize to chronically sun-damaged (CSD) skin on the head and neck, whereas BRAF-mutant melanomas are more common in areas of intermittent sun exposure." (PMID 34210801, 2021). "Our findings facilitate a more thorough understanding of the development of the complex mechanisms leading to acquired resistance during combined treatment in BRAF-mutant melanoma." (PMID 34885166, 2021). "Grant A. McArthur presented the 5-year results of another phase 3 trial (coBRIM) of combined BRAF-targeted therapy with vemurafenib and cobimetinib during the Society for Melanoma Research Congress at the end of 2019." (PMID 34064013, 2021). "The MEK1/2 inhibitors trametinib, binimetinib and cobimetinib have been approved for treatment of melanoma and BRAF-mutant non-small cell lung cancer, and several more MEK1/2 drugs are currently in clinical trials." (PMID 33972681, 2021). "It has previously been shown that treatment of melanoma cells with BRAF inhibitors induces metabolic reprogramming, strongly reducing glycolysis." (PMID 33741961, 2021). "GSDME-mediated pyroptosis has also been found to be prompted in melanoma through a combination of BRAF and MEK inhibitors, causing immune cell infiltration/activation and melanoma regression." (PMID 34429144, 2021). "Growth inhibition of NRASQ61R melanomas (as well as BRAF-mutant melanomas) was also achieved by administering the protein phosphatase 2A (PP2A) inhibitor, a phendione derivative, or through depletion of PP2A catalytic subunits." (PMID 34063141, 2021). "We confirm that protein levels of TF SOX2 were induced in mutant BRAF melanoma cell lines, A375 (top) and SK-Mel28 (middle), treated with BRAFi, vemurafenib, and MEKi, PD0325901." (PMID 33613844, 2021). "This 3-year analysis showed that in Chinese patients with unresectable or metastatic BRAF V600-mutant melanoma, median OS and 3-year OS rate were 17.6 months and 23%, respectively, after treatment with dabrafenib plus trametinib." (PMID 34504796, 2021). "Patients with advanced BRAF mutant melanoma treated with 1L immunotherapy have significantly longer BMFS and OS, and reduced incidence of brain metastases, compared with those treated with 1L targeted therapy." (PMID 34137219, 2021). "Conversely, the 5-year combined pooled data of COMBI-d and COMBI-v revealed that the median OS at 5 years was 25.9 months in patients with BRAF-positive melanoma on combined dabrafenib plus trametinib treatment." (PMID 34914610, 2021). "In melanoma, these small molecule inhibitors primarily include BRAF inhibitors, MEK inhibitors, CKIT inhibitors, vascular endothelial growth factor inhibitors, P13K-AKT-mTOR pathway inhibitors, cyclin-dependent kinase inhibitors, and receptor ErbB4 inhibitors." (PMID 33777924, 2021). "In the current therapeutic landscape, BRAF/MEK inhibition represents an alternative therapeutic option in patients with BRAF V600–altered melanoma." (PMID 33687443, 2021). "BRAFi leads to enhanced T-VEC oncolysis in BRAF-mutated melanoma lines, while MEKi increased T-VEC effectiveness in both BRAF-mutated and BRAF-wildtype cell lines." (PMID 33925915, 2021).
melanoma (continued). "We first tested the effect of these inhibitors on the short-term survival of BRAF mutant melanoma cells using the MTT assay." (PMID 34771678, 2021). "Several large-scale sequencing studies in melanoma identified significantly mutated melanoma genes, such as NF), ARID2, TERT or RAC beside the well-established oncogenes including NRAS, BRAF or KIT." (PMID 33578810, 2021). "Taken together, we herein propose an IMC-dependent protein immunophenotype signature that seems to hold strong biomarkering and drugging promise for mutant BRAF melanoma management in the clinic." (PMID 33922182, 2021). "In recent years, the prognosis for patients with advanced melanoma has improved; immunotherapy and targeted therapies (e.g., with V600E BRAF mutant-specific inhibitors) have resulted in significant increases in median overall survival." (PMID 34068624, 2021). "Simultaneous inhibition of multiple components of the BRAF-MEK-ERK cascade (vertical inhibition) has become a standard of care for treating BRAF-mutant melanoma." (PMID 34621046, 2021). "This is further confirmed by the analysis of YAP levels in human tumor specimens collected from patients with NSCLC and melanoma encoding BRAF V600E mutations, NSCLC patients with KRAS mutations, and NSCLC patients with wild-type BRAF and KRAS." (PMID 33467099, 2021). "This occurs through a multitude of BRAF-independent mechanisms that allow melanoma cells to maintain MAP kinase signaling." (PMID 34068774, 2021). "Vemurafenib was subsequently FDA approved for the treatment of BRAFV600 melanoma in 2011, followed by two more BRAF inhibitors (dabrafenib and encorafenib) in the years following." (PMID 34025662, 2021). "The BRAF-SCRIB subnetwork is found to regulate MAP kinase activity and ErbB signaling pathways that are linked to many cancers such as melanoma, lung, ovarian, breast, and prostate." (PMID 34906079, 2021). "Of interest, EZH2 is suggested to mediate resistance in BRAF mutant melanomas, and to cooperate with BRAF to maintain tumor progression." (PMID 34831002, 2021). "For instance, melanoma cells display metabolic diversity as up to 35–50% of wild-type, BRAF-mutant, and patient-derived cells display high oxidative phosphorylation activity, employing a respiratory metabolic strategy to meet energy needs." (PMID 34831420, 2021). "In order to identify miRNAs potentially involved in BRAF inhibitor resistance, we analyzed the miRNAome of melanoma cell lines sensitive to the BRAF inhibitor dabrafenib and their resistant counterparts." (PMID 33670365, 2021). "A phase II study of pembrolizumab, dabrafenib, and trametinib in BRAF-mutant melanoma has revealed improved PFS and OS." (PMID 34924562, 2021). "Nevertheless, a phase I/II trial study using Navitoclax in combination with dabrafenib (BRAF inhibitor) and trametinib (MEK inhibitor) is recruiting unresectable or metastatic patients with BRAF mutant melanoma (ClinicalTrials.gov, NCT01989585)." (PMID 33803452, 2021). "An additional study, using A375 melanoma cells, showed that a combination of BRAF, MEK, and aurora kinase A inhibitors impaired the formation of tumor nodules close to the epidermis and reduced the invasion of dermal structures." (PMID 34831311, 2021). "We propose that reflex BRAF testing should be performed for every melanoma patient with stages ≥IIB." (PMID 34068774, 2021). "We showed that mTORC2/RICTOR is an important therapeutic target in BRAF-mutant melanoma, particularly in those resistant to targeted therapy where RICTOR interacts with RAS." (PMID 34680615, 2021). "In vitro and animal experiments show that bilirubin can abrogate vemurafenib-induced growth suppression of BRAF-mutant melanoma cells." (PMID 34222023, 2021). "Both scenarios lead to alternative mechanisms through which melanoma cells can bypass BRAF inhibition to promote cell survival and melanoma progression." (PMID 34066022, 2021).